WNT7B (Wnt family member 7B)
Diseases named in the same sentence as WNT7B in open-access papers (continued):
Sharing a sentence is not in itself a finding about the gene and the disease.
psoriasis (1 paper, 2019). An autoimmune condition characterized by red, well-delineated plaques with silvery scales that are usually on the extensor surfaces and scalp. "In this study, we also analyzed SNPs in WNT7B, WNT10B, WNT16 and TFC7L2 to investigate a possible association with psoriasis." (PMID 31089877, 2019). "Associations between single nucleotide polymorphisms for WNT7B, WNT10B, WNT16 and TCF7L2 genes and psoriasis were tested." (PMID 31089877, 2019). "The functional contribution of WNT signaling to the pathophysiology of psoriasis needs to be studied further, but it can be speculated that WNT7B, WNT10B, TCF7L2 and WNT16 contribute to the pathogenesis of psoriasis." (PMID 31089877, 2019). "Treatment with nbUVB induced a significant increase of WNT7B (p < 0.01), WNT10B (p < 0.001) and TCF7L2 (p < 0.01) gene expression in lesional skin of patients with psoriasis." (PMID 31089877, 2019). "This study shows for the first time significant UVB induced upregulation of WNT7B, WNT10B and TCF7L2 in patients with psoriasis and suggests a potential role of these genes in psoriasis pathogenesis." (PMID 31089877, 2019). "In line with our results, WNT7B gene expression has previously been found to be lower in lesional skin of patients with psoriasis compared to non-lesional skin." (PMID 31089877, 2019). "WNT7B protein expression was more prominent in skin from healthy control subjects compared to non-lesional and lesional skin from patients with psoriasis." (PMID 31089877, 2019). "Gene expression analysis revealed significantly decreased WNT7B, WNT10B and TCF7L2 expression levels in lesional skin compared to non-lesional skin of patients with psoriasis (p < 0.001)." (PMID 31089877, 2019). "Levels of WNT7B, WNT10B, WNT16 and TCF7L2 gene expression in peripheral blood samples of patients with psoriasis were not significantly different compared to healthy individuals." (PMID 31089877, 2019). "The aim of this study was to describe the expression of WNT7B, WNT10B, WNT16 and TCF7L2 in lesional and non-lesional skin and in whole blood of patients with psoriasis compared to healthy individuals and to investigate if SNPs in these genes can be correlated to psoriasis." (PMID 31089877, 2019).
pterygium (1 paper, 2021). A wedge-shaped fibrovascular lesion arising from the bulbar conjunctiva and extending to the cornea. "Our further analysis of pathways controlled by upstream regulator TP63 suggested increased activity of the Notch and Wnt epithelial differentiation pathways in pterygium, and identified WNT7B, WNT9A, PPM1N and HES5 as likely involved." (PMID 34769520, 2021). "WNT7A expression did not change in our datasets; however, two other genes encoding Wnt ligands—WNT7B and WNT9A—were upregulated in pterygium." (PMID 34769520, 2021). "This analysis suggests increased activity of the Notch and Wnt epithelial differentiation pathways in pterygium, and identifies HES5, WNT7B, WNT9A, and PPM1N as being specifically involved." (PMID 34769520, 2021).
renal carcinoma (1 paper, 2023). A carcinoma arising from the epithelium of the renal parenchyma or the renal pelvis. "Furthermore, WNT7B was highly expressed in invasive cancer cells dysplaying VCO in a renal cancer lung metastasis mouse model, indicating a role of WNT signalling in VCO across different cancer entities." (PMID 36691028, 2023).
skin carcinoma (1 paper, 2019). "Microsatellite analyses indicate that this cancer phenotype is linked to a 20 Mb region of 129P2 chromosome 15 harboring the Wnt7b gene, which is preferentially expressed from the 129P2 allele in skin carcinomas and derived cell lines." (PMID 30926782, 2019). "mRNA analysis and immunohistochemistry show that Wnt7b is expressed in the skin carcinomas of Cdkn2ab−/− mice but not in soft tissue sarcomas." (PMID 30926782, 2019).
squamous cell carcinoma (1 paper, 2022). A carcinoma arising from squamous epithelial cells. "We found a group of tumor-specific WNT members, including a panel of squamous cell carcinomas (SCCs) specific upregulated WNT ligands and receptors, WNT5A, WNT7B, FZD7 and GPC1." (PMID 35850748, 2022).
Stroke (1 paper, 2026). Sudden impairment of blood flow to a part of the brain due to occlusion or rupture of an artery to the brain. "The results indicated that the progressive increase in the proportion of Wnt7b+ fibrotic astrocytes over time post-stroke is a primary driver for the increased stiffness of glial scar." (PMID 41346705, 2026). "We performed immunofluorescence staining of brain slices from similar anatomical locations from sham, day 7 and 14 post stroke groups and collected Wnt7b- astrocytes and Wnt7b+ fibrotic astrocytes cells from the peri-infarct area." (PMID 41346705, 2026). "Given the pivotal role of Ca2+ signaling in the regulation of the fibrotic astrocyte morphology by Piezo1, we investigated whether the Ca2+ level within astrocytes in glial scar region directly modulates the proportion of Wnt7b+ astrocytes after stroke." (PMID 41346705, 2026).
urothelial carcinoma (1 paper, 2024). A malignant neoplasm derived from the transitional epithelium of the urinary tract (urinary bladder, ureter, urethra, or renal pelvis). "Based on the expression of SDC1, LUM, VEGFA, TIMP3 and WNT7B in various urothelial carcinoma cell lines in the CCL database, we selected J82 and UMUC3 as the verification cell lines, and marked them with puromycin resistance labelling." (PMID 38183115, 2024).
uveitis (1 paper, 2018). An inflammatory process affecting a part of or the entire uvea. "As a homolog of WNT7B, WNT7A (ENSP00000285018) acts as one of the potential pathogenic factors of uveitis by interfering immune cell proliferation and maturation." (PMID 30349554, 2018). "According to recent publications, our inferred genes (WNT2, WNT16, WNT3, WNT7A, and WNT7B) are functionally related to the initiation and progression of uveitis due to their interference to the proliferation of urea and mixed immune cells." (PMID 30349554, 2018).
tumor (90 papers, 1998 to 2026). "In response to hypoxia, tumor-associated macrophages produce WNT7b, which in turn attributes to up-regulation of vascular endothelial growth factor (VEGF) by adjacent vascular endothelial cells in the tumor microenvironment." (PMID 33158279, 2020). "Here, the authors describe a genetic variant encompassing Wnt7b that synergises with Cdkn2ab loss and is required for tumour formation in these mice." (PMID 30926782, 2019). "The expression of the Wnt7b protein in myeloid cells induces tumor progression, metastasis, angiogenesis, and enhances the functionality of tumor-associated macrophages (TAMs) in humans and mice." (PMID 31684152, 2019). "To gain insight into the underlying mechanism of the cooperation between enhanced Wnt7b and Pdgfβ expression and loss of the Cdkn2ab locus we turned to defined cell culture systems: MEFs and tumour-derived cell lines." (PMID 30926782, 2019). "Additionally, WNT7B expression was inversely associated with immune cell infiltration rate and tumor neoantigen production capability." (PMID 40953263, 2025). "Therefore, we investigated genes in the Wnt pathway associated with TAD changes and found that WNT7B, a key gene in the Wnt signalling pathway, showed enhanced insulation boundary and upregulated expression in tumours." (PMID 38769659, 2024). "However, as observed in the primary tumours, in these cell clones the Wnt7b gene is transcribed with a similar allele specificity although to a lesser extent." (PMID 30926782, 2019). "We observed upregulation of CDKN2A and WNT7B in tumor tissues, potentially driven by increased proportions of basal epithelial cells, ciliated epithelial cells, and stem-like adenocarcinoma cells." (PMID 41184502, 2025). "Stratification based on M1-like and M2-like gene module scores shows that patients with higher Wnt7b expression in tumor cells tend to have higher M2-like module scores." (PMID 40953263, 2025). "In a third model, GL-261-MGH cell line, the mRNA expression of Wnt ligands was 200 to 500-fold lower than in 005GSC cell line; and Wnt7b protein level was ~10-fold lower in GL-261-MGH tumor tissue than in 005GSC tumor tissue." (PMID 40953263, 2025). "To investigate the causal role of Wnt7b in tumor cell survival in vitro and in vivo in a syngeneic model, we performed CRISPR/Cas9-mediated deletion of Wnt7b and clonal selection in 005GSC." (PMID 40953263, 2025). "In HPV16/18-positive CC cells, WNT7B is overexpressed and packaged into extracellular vesicles (EVs), contributing to tumor angiogenesis via the activation of the β-catenin signaling pathway." (PMID 40508156, 2025). "TCP1 promotes tumor migration via the Wnt7b/β‐catenin signaling pathway, enhancing cell proliferation." (PMID 41312091, 2025). "WNT7B staining in a tissue array comprising 70 GBM patient tumor tissues and 10 normal cerebrum tissues revealed that GBM tissues had elevated Wnt7b." (PMID 40953263, 2025). "RNA sequencing analysis revealed that matrix metalloproteinase 13 (MMP13) and WNT7B genes are upregulated in UPS, which are linked to enhanced cell migration and tumor aggressiveness." (PMID 39474109, 2024). "WNT7B promotes the angiogenic switch and vascular remodeling by increasing VEGFA expression on tumor-associated ECs." (PMID 38426109, 2024). "The Wnt7B protein is present throughout the tumor stroma and co-localizes with the CD68+ macrophage subtype." (PMID 39290697, 2024). "Wnt7b is upregulated in OS cell lines and assists in tumor cell proliferation, possibly by activating mTOR C1 via PI3K/Akt." (PMID 39119480, 2024). "Macrophage-produced Wnt Family Member 7B (WNT7b) is crucial for tumor progression by enhancing VEGF-A expression in endothelial cells." (PMID 39796695, 2024). "Depleting macrophages removed the primary source of Wnt7B and blocked the activation of the canonical Wnt pathway, resulting in a decrease in tumor number and size in the model." (PMID 39290697, 2024).
tumor (continued). "At recurrence of Occ53, few alterations were conserved compared to the primary tumor, including amplification of WNT7B and MAPK1 oncogenes." (PMID 37400764, 2023). "Immunohistochemical analysis of 38 iCCA cases detected Wnt3a protein in the cytoplasm of tumor cells in 92.1% of cases, Wnt5a in 76.3% of cases, and Wnt7b in all tumors." (PMID 37190050, 2023). "The analysis of 48 cases of liver fluke-derived iCCA showed that mRNA levels of Wnt3a, Wnt5a, and Wnt7b were higher in the tumor tissue than in the surrounding liver tissue." (PMID 37190050, 2023). "In turn, these stromal cells secrete Wnt ligands like Wnt3a, Wnt5a, and Wnt7b, and other factors that further activate Wnt signaling in tumor cells, creating a positive feedback loop that promotes tumor growth and progression." (PMID 37760801, 2023). "The role of WNT7B protein in the development of MM was reported in a recent study published in 2021, where an increased expression of the WNT7B gene promoted tumor growth." (PMID 37239457, 2023). "Wnt ligands that were expressed in both tumor cohorts included Wnt5a, Wnt5b, and Wnt7b foremost, in accordance with the reported expression of these ligands in mammary epithelium." (PMID 36106661, 2022). "The study showed that in ICC patients, the Wnt ligands Wnt7b and Wnt10a were highly expressed in tumor tissues." (PMID 36209344, 2022). "Immunostaining showed lower protein expression of Wnt7a, Wnt7b, Mmp7 and Ccnd2 in tumor tissues of the PRDX6 knockout group compared to the wild-type group." (PMID 36209344, 2022). "When HIFU is combined with anti-PD-1, tumor proliferation-related genes such as Wnt7b,S100a14 and Erbb2 are significantly downregulated, and newly released tumor-specific antigens, cytokines, and cell fragments act as agonists of innate immunity." (PMID 36032103, 2022). "WNT7B is involved in tumor growth promotion, immunosuppression, angiogenesis, and cancer cell dissemination." (PMID 35060926, 2022). "It directly targeted the Wnt Family member 7b (Wnt7b) oncogene, inhibited tumor growth, migration and invasion and restored cell sensitivity to doxorubicin." (PMID 35337159, 2022). "For ADAMTS12, AEBP1, COL10A1, COL11A1, CXCL11, EPPK1, and WNT7B, their expression values were higher in tumor samples than in normal samples." (PMID 35505821, 2022). "Consistent with in vitro results, circ_0082375 knockdown hampered tumor growth by regulating the miR-485-5p/Wnt7B axis." (PMID 34868669, 2021). "Other factors such as TGF-β, TNF, WNT7B, and thymidine phosphorylase promote tumor progression by recruiting and activating endothelial or other cells (such as fibroblasts) that further support angiogenesis in the tumor microenvironment." (PMID 34178692, 2021). "Screening for Wnt ligand expression by qPCR revealed that Wnt7b, Wnt9a and to a lesser extent Wnt3a, were significantly elevated in H2-c-fosLTR tumor-bearing bones and tumors." (PMID 32686768, 2020). "On the other hand, a direct correlation was reported between the expression of Wnt7b and tumor growth." (PMID 32140709, 2020). "Based on the quantitative reverse transcription-polymerase chain reaction (RT-PCR), the increase in the mRNA expression of Wnt3a, Wnt5a and Wnt7b has been shown in the CCA tissues in comparison with non-tumor tissues." (PMID 32140709, 2020). "Evidence for CRISPR/Cas Wnt7b gene inactivation is shown by the significantly reduced transcription of the canonical WNT signalling target Axin2 in edited tumour cells which can be rescued by WNT3a supplementation." (PMID 30926782, 2019). "Inactivation of the Wnt7b gene blocks the soft agar outgrowth of tumour cells to the same extent as addition of C59 and again this can be largely rescued by WNT3a conditioned medium." (PMID 30926782, 2019). "Consistent with its anti-tumor effects, PD407824 downregulated Wnt6 and Wnt7b, two genes linked to tumor progression." (PMID 29507695, 2018).
tumor (continued). "Several positive-acting ligands for this pathway, including Wnt3, Wnt3a, Wnt7b, and Wnt5a, are significantly overexpressed in tumor tissue, and mRNA for Wnt3 is about 5-fold more abundant in transgenic mammary tissue than in non-transgenic mammary tissue." (PMID 21304988, 2011). "The median expression of Wnt7b was fourfold higher in superficial tumours (n = 29) than in normal tissues (n = 8, P = 0.002) and five fold higher than in invasive tumours (n = 17, P = 0.003)." (PMID 9461004, 1998). "Moreover, PCa cells actively reprogram the bone niche by secreting exosomes and paracrine factors such as parathyroid hormone-related peptide (PTHrP) and Wnt7b, driving OBs and OCYs toward tumor-supportive phenotypes." (PMID 42291433, 2026). "Notably, we observed that insulation boundary of WNT7B was enhanced in tumour compared to normal tissue, correlating with an upregulation in its expression levels in tumour samples." (PMID 38769659, 2024). "MiR-342-5p targets Wnt7b and inhibits its expression, thus serving as a tumor suppressor." (PMID 39119480, 2024). "Moreover, tumor-associated macrophages express high levels of WNT family proteins, especially of WNT7B and WNT5A." (PMID 38426109, 2024). "Furthermore, myeloid Wnt7b caused an overexpression of VEGF-A in ECs, leading to angiogenic switching and tumor neovascularization." (PMID 38033495, 2023). "In GBM, miR-505 could inactivate the Wnt/β-catenin signaling pathway by directly targeting and inhibiting WNT7B to inhibit tumorigenesis as a tumor suppressor." (PMID 36762036, 2023). "Here, the expression of Wnt7a/Wnt7b was upregulated in tumor cells compared to a healthy colon." (PMID 36982422, 2023). "In addition, WNT7B is required for the angiogenic switch, tumor progression and metastasis in infiltrating myeloid cells." (PMID 35850748, 2022). "In addition, WNT7B is one of the key factors secreted by TAMs to promote tumor progression and metastasis, and it promotes tumor cell invasion by affecting angiogenesis." (PMID 36510315, 2022). "Wnt7a protein is mainly expressed in tumor cells, and Wnt7b is mainly expressed in macrophages." (PMID 36209344, 2022). "However, knocking down WNT7B in sorafenib-treated HCCLM3 cells drastically decreased tumor sizes and weights, which were boosted by L-HBs." (PMID 36497264, 2022). "Using IHC score in individual LUSC tumor tissue as a reference, we found that the expression profiling of WNT7B, WNT5A, FZD7 and GPC1 could be divided into four sub-clusters." (PMID 35850748, 2022). "Indeed, several upregulated genes in the H2BE76K mutant cells, such as WNT7B and PTN, are involved in promoting metastasis-associated tumor cell phenotypes, including increased clonogenicity." (PMID 33548228, 2021). "Wnt7b (Wnt family ligand) expression was upregulated by TAMs which could promote tumor neovascularization." (PMID 34965886, 2021). "Additionally, the density of blood vessels (assessed via CD31 staining) was decreased in the EV/E6-KD tumours compared with the EV/NC tumours, while Wnt7b-OE abrogated the inhibition of tumor angiogenesis by EV/E6-KD." (PMID 33234148, 2020). "Moreover, we also noticed that Wnt7b-OE in the E6-KD group promoted tumor growth; however, this promotion was abrogated by FH535 treatment." (PMID 33234148, 2020). "Particularly, Wnt7b protein was found to be present throughout the tumor tissue." (PMID 32140709, 2020). "In addition, a reduction of Cdk6 transcripts is observed in Wnt7b knockout tumour cells, which can be restored by WNT3a supplementation." (PMID 30926782, 2019). "Suppression of UBE2T inhibited Wnt5A and WNT7B, thus inhibiting tumor growth." (PMID 28427240, 2017). "Conversely, the influence of gene WNT7B in surrounding tissues is negatively correlated with poor prognosis, implying that such signals may better attract the attention of the immune system, thereby hindering tumor progression." (PMID 41184502, 2025). "However, Wnt7b-OE abrogated the inhibition of tumor growth by EV/E6-KD." (PMID 33234148, 2020).